CD40LG (CD40 ligand)
Diseases named in the same sentence as CD40LG in open-access papers (continued):
Sharing a sentence is not in itself a finding about the gene and the disease.
tumor (continued). "(ii) Higher CD40LG and IL-2 expression was observed in tumor tissues with genotype A_G than those with genotype A_A." (PMID 34830445, 2021). "Human B cells can efficiently present peptides to CD4 + T cells after activated by CD40 ligand and pulsed with tumor antigens." (PMID 34118931, 2021). "In the present study, higher CD40LG expression was observed in tumor tissues with CSF1R c.1085 genotype A_G compared to those with genotype A_A." (PMID 34830445, 2021). "Using Spearmen r ≥ 0.3 or r ≤ − 0.3 and p < 0.001 as a cut-off, we showed that CD40 is moderately co-expressed with CD40LG in the normal tissues (r = 0.44) and in the tumor microenvironment (TME, r = 0.37)." (PMID 34758832, 2021). "CD40 ligand (CD40L) gene therapy has been shown to increase tumor-infiltrating T cells in vivo and demonstrated an oncolytic effect." (PMID 35070956, 2021). "Over-expression of CD40 ligand (CD40L) on CAR-T cells increased anti-tumor efficacy through CD40L interactions with CD40 expressed on tumors." (PMID 34220853, 2021). "When stimulated by the CD40-CD40 ligand (CD40L) signaling pathway, B cells become local APCs in tumors, which maintain the survival and proliferation of tumor infiltrating T cells for durable antitumor responses." (PMID 32194857, 2020). "A more significant effect on survival and tumor growth inhibition was observed following injection of the plasmid containing cDNA of CD40 ligand, which is a potent inducer of DC‐maturation." (PMID 32123853, 2020). "In this regard, agonist CD40 antibody and the cognate CD40 ligand (CD40L) are candidates for tumor immunotherapy." (PMID 29129918, 2017). "Membrane bound CD40 ligand triggered tumor cell apoptosis via activation of JNK/activation protein-1 and stimulated the secretion of both tumor necrosis factor alpha and interferon gamma, which ultimately activated the caspase 3/7 pathway." (PMID 27494901, 2016). "CD40 ligand is another pro-apoptotic molecule that binds to CD40 expressed on the tumor cell surface." (PMID 27494901, 2016). "We previously reported in animal models a strategy for pulsing DCs with CD40 ligand-transfected tumor cells and pre-conditioning with MIP-3α-transfected tumor cells." (PMID 27558635, 2016). "This is one reason why we have been interested in also other transgenes, such as CD40 ligand (CD40L), a multifunctional protein which can cause apoptosis of tumor cells, but it can also deactivate suppressive circuits including regulatory T-cells." (PMID 24551478, 2014). "Investigators have shown effective sensitization of T-cells with profound antitumor effects when CD40 ligand (CD40L) is expressed in tumor cells." (PMID 20195476, 2010). "On this basis, engagement of CD40 on DC to induce anti-tumour immune responses is a prolific area of research and both recombinant soluble CD40 ligand and CD40 agonist antibodies have entered clinical trials." (PMID 20211016, 2010). "By mobilizing adhesion molecules, such as αIIβ3 integrin, P-selectin, and CD40 ligand, to the cell surface, thrombin enhances adhesion between tumor cells, platelets, ECs, and ECM and contributes to tumor progression." (PMID 15969748, 2005). "Despite these findings, the exact mechanisms through which CD40LG influences tumor development and immune interactions in NSCLC remain to be fully elucidated, necessitating further experimental studies to explore the potential therapeutic implications of targeting CD40LG in cancer." (PMID 41048996, 2025). "Applying pan-cancer TME signatures, non-NE TME was marked by immune infiltration including natural killer (NK) cells, B cells, and M1 tumor-associated macrophages (TAM-M1) and upregulation of immune co-activators (CD40LG, CD80) compared with hybrid-NE and NE TME." (PMID 38897168, 2024).
tumor (continued). "AGS-003 (Rocapuldencel-T), an autologous MoDC vaccine, loaded with the patient’s tumor-derived RNA in combination with CD40-ligand RNA, co-administered with sunitinib, an ICB, showed promising results in a phase 2 clinical trial in subjects newly diagnosed with advanced kidney cancer." (PMID 39696625, 2024). "GO analysis of CD40LG showed that tumor necrosis and NF-κB were primarily enriched." (PMID 37266442, 2023). "Therefore, blockade of the CD40-CD40LG axis by administering an anti-Cd40lg antibody suppressed tumor growth." (PMID 37612741, 2023). "Since CD40LG may trigger Th1-type immune responses, CD40LG can be used as a target for tumor therapy." (PMID 36253800, 2022). "Gene intersection and survival analysis showed that there were 435 DEG crosses in PTC patients and genome-wide tumor samples, only CXCL10, CD40LG, KRT14, TRAT1, and TREM2 were associated with patient prognosis, and TCGA showed that only the TREM2 expression was upregulated in PTC." (PMID 36438899, 2022). "CD40, a TNF receptor superfamily member, is expressed on APCs and is critical for their activation and proliferation, as well as an important regulator of T cell-dependent anti-tumor immunity via the interaction with CD40 ligand (CD40L) mainly expressed by CD4+ T cells." (PMID 35664746, 2022). "Moreover, OVs have been designed with additional transgenes encoding CD40 ligand (CD40L), increasing local CD40 activation within the tumor microenvironment." (PMID 35027068, 2022). "On the other hand, the VM index could upregulate immune checkpoints including CD28, CD86, BLTA and CD40LG to inhibit immune response, thus leading to tumor immune escape." (PMID 36505458, 2022). "However, in RT-qPCR the significance of both CD40LG and IL-7 was observed only before last fraction among all the tumour types." (PMID 33941218, 2021). "Compared to the group of patients without CSF1R variant, higher CD40LG expression, a surface marker of T cells, was found in the tumor tissues of patients with CSF1R c.1085 variant." (PMID 34830445, 2021). "Moreover, CD40LG has a strong anti-tumor effect on HCC and other malignant tumors, while the CD40LG-CD40L interaction has been shown to overcome tumor-specific CD4+ and CD8+ tolerance and thus induce anti-tumor immunity." (PMID 35127491, 2021). "In addition, we explored the CD40 ligand (CD40L) expression on T cells in the tumor microenvironment and found that ~ 50% and ~ 10% of CD4+ Th cells express CD40L in the YUMM3.3 and B16F10 tumors, respectively." (PMID 34092233, 2021). "Fortifying the tumor microenvironment with CD40-ligand/anti-CD40 agonist may further enhance the antitumorigenic effect of checkpoint inhibitors." (PMID 34765538, 2021). "CD154 (the CD40 ligand) plays a role in anti-tumor activity and growth inhibitory effects in breast cancer and recent studies indicate that PTBP1 may stabilize CD154 mRNA via targeting its 3′-UTR21,22." (PMID 31729427, 2019). "In addition, CD40 ligand expressing endothelial progenitor cells (EPCs) successfully migrated toward metastatic breast cancer lesions in the lung and induced tumor apoptosis." (PMID 27494901, 2016). "None the less, our data suggest that clinically available MPL, CpG, vaccines, or perhaps a recombinant human OX40 ligand or CD40 ligand could be used to safely activate the innate system, thereby enhancing the infused tumor-reactive lymphocytes." (PMID 26885368, 2016). "CD40LG might be a powerful predictive biomarker of tumor immunosenescence." (PMID 39796714, 2024). "Conversely, sporadic tumours displayed increased infiltration of protumorigenic M2-like macrophages and increased expression of immune checkpoints PDCD1LG2 and CD40LG." (PMID 41535448, 2026). "In summary, our investigation delineates the intricate functions of CD40LG within the context of LUAD, highlighting its importance in both immune modulation and direct tumor cell behavior." (PMID 41048996, 2025).
tumor (continued). "Th1 cells, having been primed by tumor-antigen–loaded antigen-presenting cells (APCs) presenting via major histocompatibility complex (MHC) class II, express CD40 ligand and secrete interferon-γ (IFN-γ)." (PMID 40428397, 2025). "Simultaneously, SPP1 downregulated CD40LG, TNFSF15, TNFRSF13B, IL6R, KLRK1, and other immune stimulants, indicating that SPP1 played a role in the evasion of tumor immunity by controlling the immunosuppressive surroundings." (PMID 38329443, 2024). "More importantly, BACH2-mediated CD28 and CD40LG signals contributed to cell migration and dissemination of T-ALL cells to the bone marrow, thus adding a new layer to the BACH2-mediated tumor immunoregulation in T-cell malignancies." (PMID 38233409, 2024). "Accordingly, the presence of VM can affect the infiltration of immune cells into the tumour through the upregulation of immune checkpoints, such as CD28, CD86, BLTA, and CD40LG, which can inhibit the immune response." (PMID 39718433, 2024). "Accordingly, bulk RNAseq analysis from tumor tissues unveiled a down-regulation of several genes that are related to B cell activation in CoPEC-positive tumors, such as CD19, CCR6, CD40LG and DOCK11." (PMID 38417029, 2024). "Their study highlighted that the interaction between T-cell CD40 ligand (CD40-L) and antigen-presenting CD40 is important for T-cell activation and, furthermore, for tumor inhibition." (PMID 39061246, 2024). "The cluster of differentiation 40 (CD40) molecule, a TNF-α receptor family member and receptor for CD40 ligand (CD40L), has been considered and tested as additional target to modulate macrophage behavior and anti-tumor immune response." (PMID 37346794, 2023). "Looking at expression data from both normal cells and tumor material, we found a striking expression correlation between LINC00892 and CD40LG." (PMID 35736637, 2022). "When CD40LG antibodies are used to disrupt the CD40/CD4OLG system’s function, it leads to the suppression of tumor cells." (PMID 35879761, 2022). "While, the paired analysis showed that expression of IL26, IL17F, KLRB1, CD40LG, JCHAIN, and NFKBIZ were significantly lower in the tumor group, compared with normal tissues." (PMID 35902909, 2022). "OVs were modified with CD40 ligand (CD40L) to induce DC maturation and evoke a tumor-specific T cell response." (PMID 35715953, 2022). "More sophisticated approaches use tumor vaccines, such as GM.CD40L, which is a cell-based vaccine composed of irradiated tumor cells transduced with GM-CSF and CD40-ligand (CD40L) genes." (PMID 29312320, 2017). "Other anti-tumor genes including OSM, TNF-α and CD40LG were regulated by miRNAs of both downregulated and upregulated." (PMID 25826780, 2015). "Except for OSM, the expression of all anti-tumor genes including TNF-α, PRF1, GZMB, FasL, TNFSF10 and CD40LG were significantly upregulated in CIK cells compared to PBMC, which were negatively correlated with expression profiles of their potential regulators." (PMID 25826780, 2015). "The interaction between the CD40-CD40 ligand has been demonstrated to regulate immune responses, and CD40 has an important effect on promoting tumor cell apoptosis or tumor growth." (PMID 25009656, 2014). "CD40 activation of APC plays an important role in driving anti-tumor T cell-mediated immune responses, and agonist CD40 antibodies which mimic the action of CD40 ligand are thought to represent promising therapeutics for novel immune strategies for cancer." (PMID 19906293, 2009). "Platelet–tumor cell interactions can occur directly, facilitated by various adhesion molecules such as P-selectin, glycoprotein IIb/IIIa (GPIIb/IIIa), integrins, and CD40 ligand (CD40L)." (PMID 40332071, 2025). "The objective of this research is to elucidate the significant role of CD40LG in NSCLC and to uncover the mechanisms through which CD40LG may influence tumor-infiltrating immune cells." (PMID 41048996, 2025).
tumor (continued). "Research indicates that increased CD40LG expression correlates significantly with the infiltration of diverse immune cell subsets, such as CD8+ T cells, CD4+ T cells, dendritic cells, B cells, and natural killer (NK) cells, within tumor microenvironments." (PMID 41048996, 2025). "Overexpression of ALYREF and YBX1 was accompanied by the upregulation of immune checkpoint inhibitors (such as CD276 and PDCD1) and downregulation of immune checkpoint stimulants (such as CX3L1, ITGB2, CD40LG and SELP), which promoted evasion of immune surveillance by these tumor cells." (PMID 38238581, 2024). "Although CD40LG and LTA exhibit dichotomous context-dependent actions on tumor progression, the efficiency of Rapamycin at this level may emerge from its immunomodulatory function." (PMID 38276004, 2024). "Incorporating CD40 ligand (CD40L) and IL-24 further amplifies immune-mediated tumor cell killing." (PMID 38731910, 2024). "The higher expression of the co-stimulatory molecule and M1 marker CD40 on CD45/CD14+ cells in the 4-culture PANC-1 spheroids could explain the therapeutic effect of CD40 ligand/agonists in the treatment of PDAC, boosting an anti-tumor response." (PMID 37519820, 2023). "We previously demonstrated that systemic immunization with a non-replicating MVA encoding CD40 ligand (CD40L) enhances innate immune cell activation and function, and triggers potent antitumor CD8+ T cell responses in different murine tumor models." (PMID 36997583, 2023). "CD40lg is one of the genes that define CD4TH1 in ProjecTIL22 and it was expressed by the subset identified as CD4TH1 in our single cell analysis, which was increasingly represented in the tumor of mice treated with CTLA4i, alone or in combination with RT." (PMID 37620372, 2023). "Meanwhile, activated platelets express CD40 ligand (CD40L) and CD62P in the cytoplasmic membrane, and the interaction with the vascular endothelium may induce tumor growth factor production and tumor metastasis." (PMID 36910598, 2023). "The novel combination of LTA, CD160, and CD40LG, may help us understand the immune status of patients with LUAD, but also optimize available tumor immunotherapies." (PMID 35879761, 2022). "In addition, the CD40 and CD40 ligand (CD40L) interactions between CAR-T cells and host antigen-presenting cells (APCs) as well as tumor cells also play an important role in immune activation and the release of cytokines." (PMID 35757715, 2022). "In conclusion, we found that analyzing tumor expression of LTA, CD160, and CD40LG represents a novel immune signature that may be useful for predicting prognosis and response to immunotherapy in patients with LUAD." (PMID 35879761, 2022). "After administration of a BRAFi in a BRAF-mutant melanoma model, CD40 ligand and interferon-gamma expression was increased on intratumoral CD4+ tumor-infiltrating lymphocytes (TIL), and regulatory T-cells and myeloid cells were decreased, suggesting anti-tumor modulation of the TME." (PMID 36505793, 2022). "CAR T cells engineered to express APC-activating proteins—such as CD40 ligand (CD40L), TLR agonists, or cytokines—may provide that extra kick required for full APC maturation within the tumour." (PMID 34885108, 2021). "Therefore, we analyzed the levels of expression of IL-2, IL-2RA and CD27 together with CD40LG and the anti-apoptotic regulator BCL2L1 on CD8+ TILs isolated from peripheral blood and tumor tissues of Bhi OPSCC patients (n = 4; Cohort 3)." (PMID 31623665, 2019). "GM.CD40L, a human bystander cell line created at the Moffitt Cancer Center that expresses both granulocyte-macrophage colony-stimulating factor (GM-CSF) and CD40 ligand (CD40L), has been used to generate an allogeneic tumor cell-based vaccine formulation." (PMID 30209589, 2018).
tumor (continued). "Consistently, we have found 3 tumor suppressive genes which were significantly up-regulated in CIKIL-2 including tumor necrosis factor ligand superfamily member 10 (TNFSF10), CD40 ligand (CD40LG) and interferon regulatory factor 7 (IRF7)." (PMID 25108500, 2014). "In addition, there are angiogenesis‐related markers, including ANGPT1, CD40LG, HIF1A, CCL5, and GPR87, which could contribute to tumour vascularisation." (PMID 40754672, 2025). "Furthermore, the CD40 ligand (CD40L, CD154) induces apoptosis of tumor cells." (PMID 37046608, 2023). "In a lymphoma mouse model, it is shown that intratumoral injection of TriMix mRNA, encoding costimulatory molecules CD70, CD40 ligand, and constitutively active toll-like receptor 4 (TLR4), induces systemic tumor-specific T cell responses independent of the co-delivery of tumor antigen." (PMID 34262573, 2021). "Moreover, up-regulated expressions of CD40LG and IRF7 may make for improved tumor cytolytic function of CIKIL-2 through type I interferon signaling." (PMID 25108500, 2014). "Thus CD40LG and IFR7 may work synergically to improve the tumor cytotoxic effect of CIKIL-2." (PMID 25108500, 2014). "In contrast, members of the TNF receptor superfamily (TNFSF), which mediate the noncanonical NF-κB pathway, a potential tumor-promoting mechanism (NCR3, CD40LG, LTA, LTB, and TNFRSF13C), were observed in East Asian and Mixed ancestry populations (TCGA)." (PMID 41387728, 2025). "In contrast, CD40LG is moderately correlated with PAX5 (B cells, r = 0.45 and 0.46 in normal and tumor tissues, respectively), but not BATF3 (dendritic cells)." (PMID 34758832, 2021). "However, it is also notable that a series of genes that are expressed in activated CD8+ T cells (Gzmb, Prf1, Il2, Ifng, Tnf, Fasl) or in activated CD4+ T cells (Tgfb1, Cd40lg, Il2, Ifng, Tnf, Fasl) were not upregulated in the relevant CD8+ and CD4+ clusters in tumours versus normal." (PMID 40473819, 2025). "However, there are several factors that might potentially affect the process even in vitro culture of DCs with tumor necrosis factor (TNF) or GM‐CSF and CD40 ligand (CD40L) did not enhance the expression of costimulatory molecules, suggesting that tumor cells impair DCs' differentiation." (PMID 38351552, 2024).